RN7SL305P (RNA, 7SL, cytoplasmic 305, pseudogene)
Gene: Miscellaneous RNA gene on chromosome 22 (31,981,147 to 31,981,427, reverse strand). Ensembl gene ENSG00000240647.
Homologues: Orthologues: chimpanzee Metazoa_SRP (98% identical), macaque Metazoa_SRP (94% identical). Paralogues in human: RN7SL1 (79% identical), RN7SL2 (79% identical), RN7SL851P (79% identical), RN7SL3 (79% identical), RN7SL44P (79% identical), RN7SL451P (79% identical), RN7SL575P (78% identical), RN7SL49P (77% identical), RN7SL664P (77% identical), RN7SL709P (77% identical), RN7SL70P (77% identical), RN7SL186P (77% identical), and 704 more.